TNF (tumor necrosis factor)
Diseases named in the same sentence as TNF in open-access papers (continued):
Sharing a sentence is not in itself a finding about the gene and the disease.
tumor (continued). "Dysbiosis can stimulate the activation of tumor-associated macrophages (TAMs) and the accumulation of pro-inflammatory factors such as IL-6 and TNF-α, which promote OC progression by inducing EMT." (PMID 39497925, 2024). "Depending on dose and disease type, TNF-α can cause tumor eradication and progression in cancer patients." (PMID 38398617, 2024). "TNF is a type of cytokine secreted by macrophages or lymphocytes in the body that can kill tumor cells or cause necrosis of tumor tissues, and includes TNF-α and TNF-β." (PMID 38429828, 2024). "A new cIAP1/2 and XIAP antagonist called ASTX660 makes HNSCC tumour cells more susceptible to TNF‐, TRAIL‐ and FasL‐induced cell death." (PMID 38044583, 2024). "In contrast, a Zn-deficient diet enhanced the frequency of tumor-infiltrated IFN-γ+ TNF-α+ CD4+ T cells, while the intake of high Zn reduced the frequency of these cells." (PMID 39247196, 2024). "Metastasis of the LLC also involves the powerful stimulation of tumor-associated macrophages, which produce IL-6 and TNFα by activating TLR-2 and TLR-6." (PMID 38891915, 2024). "Even when Rap1B-deficient tumor ECs are treated with TNF-α, VEGF-A cannot suppress TNF-α-induced expression of ICAM1 or VCAM1." (PMID 39337337, 2024). "Several studies have shown that inflammatory cytokines, including IL-1, IL-6, TNF-α, and IL-25, are crucial in increasing tumor-associated inflammation, metastasis, angiogenesis, and apoptotic induction." (PMID 39267848, 2024). "Pro-inflammatory cytokines like IL-1, IL-6, and TNF-α, produced by various cell types including immune cells (e.g., macrophages and T cells), cancer-associated fibroblasts (CAFs), and tumor cells themselves, promote inflammation and tumor cell proliferation." (PMID 39200315, 2024). "Tumor-associated macrophages (TAMs) also secrete proangiogenic factors and immunosuppressive cytokines (TGFβ, IL-6, IL-10, tumor necrosis factor α [TNFα])." (PMID 39519018, 2024). "Cannabinoids inhibit the release of TNF-α (Tumor Necrosis Factor), which is a type of tumor necrosis factor that causes the killing and necrosis of tumor cells." (PMID 38968285, 2024). "Mechanistically, EMT drives repression of Irf6, making the tumor cells less susceptible to the pro-apoptotic effects of T cell-derived TNF-α." (PMID 38378697, 2024). "TNF-α, it is a proinflammatory cytokine that is initially associated with the killing of tumor cells and plays a key role in regulating proinflammatory and anti-inflammatory mediators." (PMID 38590775, 2024). "In chronic inflammation caused by cancer cachexia, inflammatory cytokines such as TNF-α and IL-6 promote muscle loss and tumor growth." (PMID 39272894, 2024). "This group concluded that VCAN was associated with poor prognosis through induction of tumor development by reducing TNF-mediated cellular apoptosis." (PMID 38957320, 2024). "Especially, high numbers of infiltrating TIGIT+CD8+ T cells into the tumour diminish the anti-tumour immunity, associated with a low expression of TNF-α, IFN-γ, and GzmB." (PMID 38893071, 2024). "In obesity-associated tumors, the pro-inflammatory and tumor-promoting effects of TNFα seem to be more prominent." (PMID 39253073, 2024). "Tumor-associated macrophages (TAMs) secrete TGFβ and tumor necrosis factor alpha (TNFα), which synergize with TGFβ to promote EMT." (PMID 39598229, 2024). "When TNF-α was first identified in 1975, it was observed to cause tumor necrosis and hemorrhage, leading to its classification as a highly effective anticancer cytokine." (PMID 39830670, 2024). "NF-κB and TNFα also showed activity across myeloid subsets, but more marked in classical monocytes and tumor-associated macrophage (TAM)." (PMID 39161957, 2024).
tumor (continued). "TNF causes tumor cell necrosis and apoptosis as well as host defense against bacterial and viral infection." (PMID 38540714, 2024). "TNF-α is linked to tumor progression, metastasis, angiogenesis, and tumor resistance to immunotherapies." (PMID 39767777, 2024). "Tumor necrosis factor-alpha (TNF-α) and interleukin (IL)-6 levels are elevated in the tumor tissues and sera and associated with poor survival, increased tumor burden, and disease progression in patients with CRC." (PMID 39272794, 2024). "As a pro-inflammatory cytokine produced by both tumor and host cells, TNFα is implicated in inflammation and subsequent tumor development and progression." (PMID 39105847, 2024). "When tested in vitro, Ptges-KO and Ptger4-KO tumor cells were 2- to 5-fold more susceptible to TNF-α–induced killing compared with parental and control EV cell lines." (PMID 39298269, 2024). "Studies had also demonstrated that peritumoral features were associated with the tumor necrosis factor (TNF) signaling pathway, which was involved in tumor angiogenesis, invasion, and metastasis." (PMID 38424285, 2024). "In a preclinical study, HER2 BAT-associated activated T cells demonstrate anti-tumor cytotoxicity, effective intratumoral trafficking, and secretion of cytokines such as IFNγ, TNFα, and GM-CSF, upon tumor engagement." (PMID 38801069, 2024). "TNF-α is an essential pro-inflammatory cytokine secreted by stromal cells, tumor-associated macrophages, and cancer cells." (PMID 38541912, 2024). "Mechanistically, Ptges- and Ptger4-KO tumor cells exhibited altered T and myeloid cell attractant chemokines, became more susceptible to TNF-α–induced killing, and exhibited reduced adenosine synthesis." (PMID 39298269, 2024). "HLA-E expression in tumor cells can be regulated in response to immune associated factors such as IFNγ, TNFα, IL-1β and IL-27, which are also associated to GMM educated immune cells." (PMID 39229258, 2024). "The tumor necrosis factor (TNF) produced by neutrophils triggers an excessive production of C-X-C motif chemokine ligand 1 (CXCL1) in both tumor cells and cancer-associated fibroblasts (CAFs), resulting in the suppression of T cells." (PMID 39001498, 2024). "The analysis revealed elevated levels of pro-inflammatory cytokines, including interleukin-6 (IL-6) and tumor necrosis factor-alpha (TNF-α), which are often linked to chronic inflammation and tumor progression." (PMID 39795579, 2024). "These causes include 1) Direct tumor influence: Tumor cells produce cytokines like IL-1, IL-2, IL-6, and TNF-α, promoting tumor growth, disrupting normal cellular metabolism, and compromising bodily functions." (PMID 39872045, 2024). "According to enrichment analysis, we found that tumor-associated inflammatory pathways, such as the IL-17, TNF, NF-κB signaling pathways and neutrophil extracellular trap formation-associated pathways, were markedly activated." (PMID 38515216, 2024). "Although findings on TNF-α are sometimes contradictory, the cytokine is generally associated with higher tumor stages and has potential as a prognostic marker." (PMID 39594709, 2024). "Two cytokines that act through the NFκB pathway are TNFα, which is produced by tumor-associated macrophages (TAMs), and IFN-γ, which is produced by tumor-infiltrating T and natural killer (NK) cells." (PMID 39247817, 2024). "Because of the inflammatory state of the TME in PDAC, tumor cells secrete pro-inflammatory substances like tumor necrosis factor-alpha (TNF-α) and IL-12, causing the recruitment of neutrophils to the location of the tumor." (PMID 38835055, 2024). "The proinflammatory microglia produced high concentrations of nitric oxide (NO) and high levels of the proinflammatory cytokines TNF-α, IL-6, and IL-1β, and caused further DNA damage and promoted the apoptosis rate of tumor cells." (PMID 38750472, 2024).
tumor (continued). "Despite numerous conflicting reports on the impact of CD4 + Th1 cells on the survival outcomes of PDAC patients, mechanistically, these cells are linked with key cytokines IL-2, IFN-γ, and TNF-α, contributing to anti-tumor immunity." (PMID 38833018, 2024). "TNF production has been shown in preclinical investigations to cause de-differentiation processes, which in turn cause immunogenicity reduction, tumor relapse, and loss of melanocytic markers." (PMID 38139369, 2023). "The authors demonstrated a positive effect on the survival of tumor bearing animals and a reduction of the toxicity associated with TNFα in vivo." (PMID 36854896, 2023). "Several relative experiments showed that TNF‐α and IL‐6 declined apparently in the serum of cancer cells in mice after intragastric omeprazole which implied that PPIs inhibit the tumour progression caused by fat metabolism." (PMID 35961680, 2023). "High expression of TNF-α in the serum of cancer patients and in pre-cancerous and tumor tissues has been associated with tumor proliferation, angiogenesis, invasion and metastases, and resistance to chemotherapeutic agents in several cancers." (PMID 37867861, 2023). "The anti-tumour efficacy of 11B12-1 was subsequently validated in a combination with an oncolytic adenovirus encoding IL-2 and TNFα (TILT-123)." (PMID 36817448, 2023). "TNF-α is a crucial proinflammatory cytokine that promotes tumor progression by modulating tumor-associated inflammatory responses." (PMID 36831664, 2023). "As a result of this study, we evaluated the expression of the splice variants of TNFRSF1A and TNFRSF1B receptor-encoding genes for TNFα on tumor cell lines of different origins in intact and TNFα-stimulated cultures." (PMID 37239433, 2023). "RDW was proven to be associated with IL‐6, TNF‐α, hepcidin and other cytokines that can affect the biological behavior of tumor cells in previous study." (PMID 37143237, 2023). "The PDPN-deficient CD8+ tumor-infiltrating lymphocytes exhibited increased tumor necrosis factor production, while the abundance of exhausted T lymphocytes was decreased." (PMID 37894446, 2023). "Tumour necrosis factor-α (TNF-α), mainly generated by activated mononuclear macrophages and other cells, was a cytokine capable of causing haemorrhagic necrosis of tumour tissue cells." (PMID 37162544, 2023). "Numerous studies have implicated TNF-α for tumour progression based on its potential to encourage the mass migration of myeloid cells into the microenvironment and promote vascularisation via increasing the production of VEGF." (PMID 37680708, 2023). "The inflammatory cytokines TNF-α and IL-1β are commonly found in the inflammatory environment of various tumors and are often thought to be associated with tumor promotion." (PMID 37081962, 2023). "M1-type macrophages have a pro-inflammatory phenotype and inhibit tumor growth and metastasis by secreting associated inflammatory cytokines such as tumor necrosis factor-α (TNF-α) and interleukin-1β (IL-1β), which can be induced in vitro by LPS or IFN-γ." (PMID 37351109, 2023). "Tumour necrosis factor-alpha (TNF-α), a pro-inflammatory mediator, regulates cellular communication within the tumour microenvironment and is associated with the progression of the metastatic phenotype." (PMID 36765584, 2023). "The polarized microglial cells release high levels of O2 radicals to contribute to the genomic mutations and enhance the expression of IL-6 and TNF-α to support tumor survival." (PMID 37012233, 2023). "Further research is needed to explore the association between increased TNF-α and tumor progression in patients with OSA and cancer." (PMID 36831404, 2023). "In this review, we will focus on the interactions between MCs, NK cells, and neuronal structure and their communications via proinflammatory cytokines, including TNFα, IL-1β, and IL-6, in peripheral neuropathy in association with tumor immunology." (PMID 37628724, 2023).
tumor (continued). "This T cell exhaustion phenotype was corroborated by the significantly lower concentrations of various T-cell associated inflammatory cytokines, such as IFN-γ, TNF-α, IL-6 and IL-17A, in the plasma of tumor-bearing aging mice." (PMID 37752597, 2023). "A nanoparticle delivery mechanism was formulated comprising TNF-alpha loaded PEG coated gold NPs designed to enhance tumor destruction while mitigating the systemic toxicity associated with TNF-alpha." (PMID 37959284, 2023). "PGE2directly induces IL-10 release from macrophages, decreases IL-6 and TNF-α release, controls tumor-associated inflammation, and decreases the body’s anti-tumor immune response." (PMID 37153586, 2023). "The M2d sub-type, commonly referred to as tumor-associated macrophages (TAMs), promotes tumor progression by secreting TNFα, IL6, IL-10, TGFβ, and Vascular Endothelial Growth Factor A (VEGFA)." (PMID 37371552, 2023). "Tumor associated macrophages (TAMs) play a vital role in the production of TNF-α which can be associated with increased stemness in OC." (PMID 38170015, 2023). "For instance, in pancreatic cancer, vagotomy, which involves the cutting of the vagus nerve, can lead to increased tumor growth, worsened survival, and higher levels of tumor-associated macrophages and TNF-α." (PMID 38099290, 2023). "Many studies have demonstrated that IL-6 and TNF-a enhance tumor cell adhesion and that this is associated with an increased expression of ICAM-1 and VCAM-1 by mesothelial cells." (PMID 38068319, 2023). "Mechanistically, tumor-associated macrophages (TAMs) activate NF-ĸB by secreting TNFα/IL-1β in the liver microenvironment and transcriptionally upregulate OTU deubiquitinase 1 (OTUD1) expression, which enhances FGL1 stability via deubiquitination." (PMID 37872170, 2023). "Cells stressed by low‐dose irradiation create an highly cytokine driven surrounding swimming with effector CD4 and CD8+ T cells, ICD proteins, neoantigens, various TNF and IL factors mediating which cause secondary cytolytic tumor killing." (PMID 36411943, 2023). "High doses of locoregional TNF-α can cause hemorrhagic necrosis via selective destruction of tumor blood vessels by generating specific T-cell antitumor immunity." (PMID 37994159, 2023). "TNFerade is an adenovirus-deficient vector that carries the gene directly into the tumor for the production of tumor necrosis factor (TNF) alpha, a cytokine with anticancer activity that is produced by the inflammatory system." (PMID 37835413, 2023). "Inflammatory markers like high-sensitivity C reactive protein (hs-CRP), interleukin-10 (IL-10), interleukin-6 (IL-6), and tumor necrosis factor-alpha (TNF-α) reflect the chronic inflammation associated with tumor initiation and progression." (PMID 37764678, 2023). "For example, M1 TAMs have the ability to generate soluble factors, including reactive oxygen species (ROS), nitric oxide (NO), TNF-α, and IL-1β, which can cause apoptosis, DNA damage, or cytotoxicity, leading to the direct killing of tumor cells." (PMID 37234776, 2023). "In this study, it was observed that increased tumor cell death caused by RG6146 was dependent on CD8+ T-cell-derived tumor necrosis factor (TNF)." (PMID 36672677, 2023). "Genes associated with a pro-inflammatory tumour microenvironment included TNF, IL6, IL18, NLRP3, IL1B and CASP1 which were also comparable between sporadic and NF2-SWN VS samples." (PMID 37680691, 2023). "TNF-α is a proinflammatory cytokine that has been implicated in tumor development, survival, malignancy." (PMID 37867861, 2023). "Cancer-associated fibroblasts (CAFs) and tumor-associated macrophages (TAMs) significantly contribute to this process, secreting pro-inflammatory cytokines such as interleukin-6 (IL-6) and tumor necrosis factor-alpha (TNF-α)." (PMID 37760852, 2023). "NFKB2 has frequent mutations in cancers, and it is related with abnormal TNF signal transduction and tumor diseases." (PMID 36323529, 2023).
tumor (continued). "The infiltration of CD8+ T cells and CD4+ Th1 cells at the tumor site is a hallmark of a favorable tumor prognosis, due to their production of the cytokines IFNγ and TNFα, which can effectively induce the cell cycle of tumor cells to arrest in the G1/G0 phase." (PMID 37545500, 2023). "Tumor necrosis factor α (TNF-α) is a tumor necrosis factor that can cause tumor necrosis with high doses and repeated local injections." (PMID 37854883, 2023). "Interference with the nuclear factorκB (NF-κB) signaling pathway or association with tumor necrosis factor-α (TNF-α) can result in M1-type TAMs that promote tumor regression." (PMID 37880233, 2023). "To further elucidate the signaling underlying the β3-AR/PD-L1 cross-talk in our tumor model of NB, we first assayed in vitro the expression of PD-L1 on N2A tumor cells following TNF-α and IFN-γ treatment." (PMID 36854895, 2023). "Various inflammatory molecules like IL-6, TGF-β, IFN-γ, and TNF-α are associated with tumour development, while tumour recurrence is associated with its spread." (PMID 37742025, 2023). "The proinflammatory status of the TME is also associated with TNF-α that promotes colorectal carcinogenesis and tumor cell migration via NF-kB and Wnt/β-catenin signaling pathways activation." (PMID 37760840, 2023). "Systemic administration of TNFα in cancer therapy has been avoided because of its pro-inflammatory actions but TNF destroys tumor-associated blood vessels by apoptosis and improves vascular permeability to cytotoxic drugs." (PMID 37400761, 2023). "Once recruited, tumor associated neutrophils (TAN) release tumor necrosis factor (TNF) which is associated with cancer metastasis to lymph nodes." (PMID 36838253, 2023). "In PDAC, TNF-α induces endothelial-mesenchymal transition promoting stromal development of the tumor, and therefore it is consistent that increased monocytes are associated with increased concentration of TNF-α and thus more aggressive tumor growth." (PMID 36672313, 2023). "For example, HSP27 shows biological effects on monocytes by causing IL10 and TNFα secretion and blocking monocyte differentiation to normal dendritic cells and tumor-associated macrophages to promote cancer progression and chemoresistance." (PMID 37893013, 2023). "A study conducted on patients with inflammatory BC demonstrated a direct association between TNF-α and the presence of tumor cells expressing EMT markers." (PMID 38406175, 2023). "DEX caused a decrease in tumor size, tumor weight, and IL-1β and TNF-α levels and an increase in NK cell activity and IFN-γ level." (PMID 37528154, 2023). "More importantly, cytotoxicity indicators (GZMB, IFN‐γ, TNF‐α, and Perforin) of CTLs were also reinforced in murine tumor with BCAT2 loss and combination treatment compared to corresponding control." (PMID 36642843, 2023). "A series of cytokines, including TNF-α and IL-6, have been associated with the differentiation and proliferation of tumor cells and tumor neoangiogenesis in CRC." (PMID 38068319, 2023). "TNF-α is an anti-tumor multi-function factor which can promote the tumor necrosis and a large amount of TNF-α can cause serious inflammatory reactions such as blood pressure increase and tissue necrosis." (PMID 37726647, 2023). "High TNF-α gene expression is associated with Stage III and IV neoplasms compared to earlier tumor stages, and TNF-α expression is increased in the serum of CRC patients." (PMID 37176567, 2023). "Our results demonstrated that tumor-associated MCs harbor a main connective tissue phenotype and release high amounts of Interleukin (IL)-6 and Tumor Necrosis Factor (TNF)-α." (PMID 37730723, 2023).